LSM2 (LSM2 homolog, U6 small nuclear RNA and mRNA degradation associated)
Diseases named in the same sentence as LSM2 in open-access papers (continued):
Sharing a sentence is not in itself a finding about the gene and the disease.
tumor (8 papers, 2018 to 2025). "Specifically, in glioblastoma (GBM), LSM2 expression was positively correlated with tumour purity and neutrophil infiltration, but negatively correlated with CD4+ T cell infiltration." (PMID 40365337, 2025). "In contrast, in LGG, LSM2 expression positively correlated with tumour purity (r = 0.154, p < 0.001) and CD4+ T cell infiltration (r = 0.161, p < 0.001), and negatively correlated with CD8+ T cell infiltration (r = -0.178, p < 0.001)." (PMID 40365337, 2025). "Previous studies have reported that RBPs like LSM2 are involved in the regulation of mRNA stability, splicing, and translation, all of which are crucial for tumour progression." (PMID 40365337, 2025). "This suggests that LSM2’s regulatory role in RNA splicing affects adhesion molecules, which in turn influences tumour cell migration and invasion." (PMID 40365337, 2025). "Pathway enrichment in adherens junctions, focal adhesions, and complement cascades suggests that LSM2 affects tumour cell migration and invasion by influencing interactions with the tumour microenvironment." (PMID 40365337, 2025). "In GBM, LSM2 expression exhibited a significant positive correlation with tumour purity (r = 0.301, p < 0.001) and neutrophil infiltration (r = 0.116, p < 0.05), and a weak negative correlation with CD4+ T cell infiltration (r = -0.115, p = 1.85e-02)." (PMID 40365337, 2025). "The expression profile of LSM2 mRNA was compared between tumor and normal tissues in public databases, such as TCGA, GEO, and BioGPS." (PMID 37312186, 2023). "Another study also confirmed a significant relationship between upregulated LSM2 expression and advanced tumor stage." (PMID 36371223, 2022). "In this study, we identified a significant correlation between the overexpression of LSM2 and increasing tumor stages." (PMID 34638387, 2021). "Targeting LSM2 could potentially disrupt its regulation of splicing and related pathways, leading to reduced tumour cell proliferation, invasion, and immune evasion." (PMID 40365337, 2025). "This expression pattern suggests that LSM2 may play a key role in the proliferation, differentiation, or other nuclear functions of tumour cells." (PMID 40365337, 2025). "By modulating splicing events, LSM2 may help maintain the integrity of cytoskeletal structures and nuclear functions that are critical for tumour progression." (PMID 40365337, 2025). "Another study revealed that the promoter cytosine phosphate guanosine island (CGI) of LSM2 might be a novel candidate for OV hypomethylated tumor markers." (PMID 37312186, 2023). "The aberrant DNA methylation of LSM2 in the OV might lead to increased LSM2 expression, thereby promoting tumor development." (PMID 36371223, 2022). "Additionally, the mechanisms by which LSM2 influences immune responses within the tumour microenvironment remain unclear and should be investigated further." (PMID 40365337, 2025). "Similarly, a previous study revealed that LSM2 is correlated with increasing tumor stage in BRCA." (PMID 37312186, 2023). "In addition, high expression of LSM2 was markedly related to high tumor stage." (PMID 36371223, 2022). "In this study, Tcm infiltration was positively correlated with LSM8 and LSM12 but negatively correlated with LSM2 and LSM4, which was consistent with the effect of genes on tumor prognosis." (PMID 36371223, 2022). "LSM2 and LSM4 proteins were overexpressed in tumor tissues with similar patterns in BRCA patient samples in the HPA dataset." (PMID 34638387, 2021). "In GBM, LSM2 could promote neutrophil infiltration while inhibiting CD4+ T cell infiltration, which may facilitate immune evasion by the tumour." (PMID 40365337, 2025).
nervous system disease (1 paper, 2022). "The nervous system disease class consists of proteins APP, DYNC1H1, DYNC1I2, HINT1, LSM2, RNF11, SNCA in between 30% and 40% association." (PMID 34918006, 2022).
LSM2 also shares sentences with these, for which no sentence is quoted: lupus (9 papers); mixed connective tissue disease (6); infection (4); Autoimmunity (3); Alzheimer disease (2); connective tissue disease (2); lung adenocarcinoma (2); Nager syndrome (2); retinitis pigmentosa (2); scleroderma (2); spinal muscular atrophy (2); systemic sclerosis (2); viral infection (2); acrofacial dysostosis (1); adenoid cystic carcinoma (1); astrocytomas (1); blood cancers (1); Cerebellar atrophy (1); cerebrocostomandibular syndrome (1); cervical carcinoma (1); colon cancer (1); colorectal cancer (1); congenital heart block (1); cyst (1); developmental delay (1); diabetes (1); diffuse large B-cell lymphoma (1); Down syndrome (1); esophageal carcinoma (1); interstitial lung disease (1).
A further 34 diseases each share a sentence with LSM2 in 1 paper.